AMZ2P1 (AMZ2 pseudogene 1)
Synonyms: FLJ32065
Gene: Transcribed unprocessed pseudogene on chromosome 17 (64,968,222 to 64,973,517, reverse strand). Ensembl gene ENSG00000214174.
Diseases named in the same sentence as AMZ2P1 in open-access papers:
AMZ2P1 is named in the same sentence as 2 diseases in open-access papers, as found by Europe PMC text mining. Sharing a sentence is not in itself a finding about the gene and the disease. The quoted sentences say what the papers report.
cervical cancer (1 paper, 2021). A primary or metastatic malignant neoplasm involving the cervix. "Finally, we further screened the 2 DE RNAs (AMZ2P1 and HDAC5) closely associated with the development of cervical cancer by clinical sample." (PMID 33833775, 2021). "Finally, combined with cluster analysis results, we further screened 2 DE RNAs (AMZ2P1 and HDAC5) using clinical samples, suggesting that AMZ2P1, and HDAC5 may act as diagnostic biomarkers for the development of cervical cancer." (PMID 33833775, 2021). "Finally, AMZ2P1 and HDAC5 were identified to be related to prognosis and cervical cancer development using clinical samples." (PMID 33833775, 2021).
AMZ2P1 also shares sentences with these, for which no sentence is quoted: cervical squamous cell carcinoma (1 paper).